SP1 (Sp1 transcription factor)
Diseases named in the same sentence as SP1 in open-access papers (continued):
Sharing a sentence is not in itself a finding about the gene and the disease.
Sepsis (15 papers, 2015 to 2026). Sepsis is defined as life-threatening organ dysfunction caused by a dysregulated host response to infection. "Consensus clustering identified four stable sepsis physio-phenotypes (SP-1-SP-4) associated with distinct autonomic and peripheral vascular signatures." (PMID 41928797, 2026). "The ZFAS1/Notch signaling pathway is subject to regulation by the transcription factor Sp1, which ameliorates myocardial injury associated with sepsis." (PMID 41041277, 2025). "ZFAS1, activated by SP1, aggravates the progression of sepsis-induced cardiac dysfunction via targeting miR-590-3p/AMPK/mTOR signaling-mediated autophagy and pyroptosis of cardiomyocytes." (PMID 40041174, 2025). "Transcription factor SP1 ameliorates sepsis-induced myocardial injury and intestinal barrier dysfunction." (PMID 39262873, 2024). "A transcription factor, specificity protein-1, i.e., SP1, reduces intestinal barrier dysfunction, oxidative stress, and inflammatory response after sepsis by upregulating HDAC4 while inhibiting the high mobility group box one protein (HMGB1) expression." (PMID 38397377, 2024). "Zinc finger antisense 1 (ZFAS1), which is activated by the transcription factor SP1, can induce pyroptosis in cardiomyocytes by targeting the miR-590-3p/AMPK/mTOR signal, and aggravate cardiac dysfunction caused by sepsis." (PMID 37872948, 2023). "Actively, SP1 was overexpressed in sepsis and SP1 depletion relieved LPS-induced cardiomyocyte damage." (PMID 35091534, 2022). "Through a series of assays, we testified the mechanism of sepsis-induced myocardial injury from miR-124-3p/SP1/HDAC4/HIF-1α axis." (PMID 35091534, 2022). "In this case, we targeted to explore in detail the relative mechanism of microRNA (miR)-124-3p in sepsis-induced myocardial injury via the specific protein 1/histone deacetylase 4/hypoxia-inducing factor 1α (SP1/HDAC4/HIF-1α) axis." (PMID 35091534, 2022). "SP1 is the positive regulator of ZFAS1 that worsens cardiac dysfunction induced by sepsis, suggesting the involvement of SP1 in sepsis." (PMID 35091534, 2022). "The results showed that the SP1 level had the most significant difference between the control and sepsis groups among several transcription factors." (PMID 33954185, 2021). "The hypocalcemia of critically ill patients with burn injury or sepsis is associated with CASR gene upregulation by TNF-alpha and IL-1beta via kappaB elements, and by IL-6 via Stat1/3 and Sp1/3 elements in the CASR gene promoters, respectively." (PMID 27679579, 2016). "Therefore, SP1 interacts with members of the microRNA family, participating in the regulation of sepsis-induced myocardial damage, but regulating different microRNAs will have different effects." (PMID 39062521, 2024). "Further studies are at wanting to deeply decode the miR-124-3p/SP1/HDAC4/HIF-1α axis in sepsis." (PMID 35091534, 2022). "However, except for this research, there are various reports mentioning the concrete mechanism of SP1 in sepsis." (PMID 35091534, 2022). "Moreover, SP1 also contributes to the regulation of sepsis-induced myocardial injury." (PMID 39062521, 2024). "Additionally, SP1 could activate zinc finger antisense 1, thereafter to accelerate the development of cardiac dysfunction induced by sepsis." (PMID 35091534, 2022). "The research discovered that SP1 interacts with miR-124-3p to inhibit histone deacetylase 4 (HDAC4), a promising therapeutic target for sepsis." (PMID 39062521, 2024). "In a word, miR-124-3p targeted SP1 to regulate HDAC4 and HIF-1α, thereby attenuating the pathology of sepsis-induced myocardial injury." (PMID 35091534, 2022). "Mechanistic insights unveiled that SP1 activated ZFAS1 expression, thereby mediating cardiomyocyte pyroptosis and autophagy through the miR-590-3p/AMPK/mTOR signaling pathway, ultimately exacerbating sepsis-induced cardiac dysfunction." (PMID 39062521, 2024).
Sepsis (continued). "Enlightened by those studies, we would wonder that whether miR-124-3p could interact with SP1, thereby affecting HDAC4/HIF-1α axis to attenuate myocardial injury in sepsis." (PMID 35091534, 2022). "miR-124-3p was lowly expressed while SP1, HDAC4, and HIF-1α were highly expressed in sepsis." (PMID 35091534, 2022). "All in all, it was certified that miR-124-3p interacted with SP1 to suppress HDAC4, thereby ameliorating sepsis-induced myocardial injury, which may related to the knockdown of HIF-1α." (PMID 35091534, 2022). "Hence, our data suggest that manipulation of SP1 or CXCR4 may be an effective approach to promote the prevention or recovery of septic myocardial injury, and thereby, serve as a potential therapeutic strategy for sepsis." (PMID 35048778, 2022). "The therapeutic effect of miR-124-3p upregulation on septic cardiomyocytes, as well as the targeting relationship between miR-124-3p and SP1 has been verified in our previous experiments, but whether SP1 was involved in miR-124-3p-mediated myocardial injury in sepsis was not clearly elucidated." (PMID 35091534, 2022). "Hence, our findings provide evidence that manipulation of SP1 or CXCR4 may be an effective approach to promote prevention or recovery of septic myocardial injury, and thereby, may serve as a potential therapeutic strategy for sepsis." (PMID 35048778, 2022).
myocardial infarction (14 papers, 2013 to 2026). Gross necrosis of the myocardium, as a result of interruption of the blood supply to the area, as in coronary thrombosis. "The reduced binding affinity of Sp1/Sp3 in the presence of the T allele of the tissue-type plasminogen activator –7351C > T polymorphism explained an increased risk of myocardial infarction in individuals carrying this allele." (PMID 30413149, 2018). "Moreover, SP1 has been implicated in regulating cardiac remodeling and myocardial fibrosis post-myocardial infarction (MI)." (PMID 39062521, 2024). "A more recent study reported that Pioglitazone (an insulin sensitizing drug with cardio protective effect, it attenuates cardiac fibrosis) increased miR-711 levels in myocardial infarction rats and miR-711 directly targeted and downregulated SP1, leading to reduced collagen-I levels." (PMID 24278182, 2013). "Additionally, SP1 may offer protection against coronary atherosclerosis and cardiac remodeling post-myocardial infarction by influencing the gene transcription of PSRC1, ABCA1, SR-BI, and P4Ha1." (PMID 39062521, 2024). "When Sp1 was knocked down and myocardial reperfusion performed, LDH release, cardiac troponin I content, myocardial infarction areas and pro-apoptotic protein expression were increased, and the left ventricular function was more serious." (PMID 32958799, 2020). "When Sp1 was knocked down after Lut preconditioning, LDH release, cardiac troponin I content, myocardial infarction area and pro-apoptotic protein expression were increased in comparison with the Lut + I/R group, and left ventricular function was greatly deteriorated." (PMID 32958799, 2020).
oral squamous cell carcinoma (14 papers, 2014 to 2025). "By inducing apoptosis through downregulation of Sp1 expression and downstream protein expression, LicA was shown to inhibit the growth of oral squamous cell carcinoma in a dose- and time-dependent manner." (PMID 36840005, 2023). "Mcl-1 is a target protein of Specificity protein 1 (Sp1) and panobinostat downregulates via Sp1 suppression in oral squamous cell carcinoma." (PMID 33806487, 2021). "In oral squamous cell carcinoma, LBH589 induces apoptosis through regulation of specificity protein 1 (Sp1) in oral squamous cell carcinoma cell lines." (PMID 26176219, 2015). "Furthermore, LicA inhibited the growth of oral squamous cell carcinoma cells through Sp1-mediated apoptosis." (PMID 36840005, 2023). "The purpose of this study was to investigate the anti-proliferative effects of 2,4-bis (p-hydroxyphenyl)-2-butenal (HPB242) on two oral squamous cell carcinoma (OSCC) cell lines, HN22 and HSC4, through regulation of specificity protein 1 (Sp1)." (PMID 24423061, 2014).
liver fibrosis (13 papers, 2013 to 2025). "This included genes associated with metabolism (Fabp1, Insr), genes associated with cell stress (Atf6, Ddit3, and Eif2ak3), genes associated with liver fibrosis (Hgf, Sp1, and Timp1) and genes associated with the inflammatory response (Tnf, Ptpn22, and Pparg)." (PMID 28686204, 2017). "Upregulation of Sp1 was found in activated HSCs of the CCl4-treated mouse model as well as CHB patients with liver fibrosis, suggesting a positive correlation between Sp1 expression and cVIM level." (PMID 38243118, 2024). "Sp1, an important transcription factor in liver fibrosis, is required for the regulation of fibrosis-related genes, such as CTGF, Col1A1, laminin and Smads32–36." (PMID 38243118, 2024). "Our collective results suggest that cVIM overexpression in liver fibrosis is partly attributable to binding of the transcription factor, Sp1, to its promoter region and stimulating transcription." (PMID 38243118, 2024). "Among these, SP1 targeting has proved beneficial against fibrosis in an animal model of liver fibrosis." (PMID 36902112, 2023). "Another study compared existing microarray datasets of hepatic RNA obtained from humans and revealed higher expression of SP1 in patients with hepatic fibrosis." (PMID 36902112, 2023). "Another study indicated a key role for SP1 in the progression of CCL4-induced hepatic fibrosis through the transcriptional promotion of TGF-β." (PMID 36902112, 2023). "The expression of these hepatic fibrosis related genes are regulated by some transcription factors, such as specificity protein 1 (SP1), NF-κB, Smads, upstream TIMP1 element 1 (UTE1)." (PMID 27175276, 2016). "SP1 is involved in the expression of ECM genes that have an important role in hepatic fibrosis progress and regulates expression of several genes that are relevant to downstream targets of TGF-β." (PMID 27175276, 2016). "We intend to focus our future research on characterization of the Sp1 protein functions in apoptosis of LX-2 cells through ARTS associated pathways, which provides a basis for study on the function of ARTS in hepatic fibrosis." (PMID 25790304, 2015). "In rodent models of kidney, lung, and liver fibrosis, SP1 targeting was shown to be a powerful anti-fibrotic strategy." (PMID 26251672, 2015). "Additionally, the upregulation of cVIM was due, at least in part, to activation of Sp1 in liver fibrosis." (PMID 38243118, 2024). "In addition, both Sp1 and cVIM were increased in vivo during liver fibrosis, indicating a positive correlation between Sp1 expression and cVIM level." (PMID 38243118, 2024). "And lastly, EMSA showed that compound 2 reduced the binding of Sp1 in the liver tissue in a dose-dependent manner, providing direct evidence that compound 2 down regulates the expression of Col 1A2 gene both in vivo and in vitro and therefore retards liver fibrosis induced by TGF-β1." (PMID 28384213, 2017). "Intravenous administration of a decoy oligonucleotide against SP1 (R-SP1 decoy ODN), effectively suppressed hepatic fibrosis in these mice by inhibition of TGF-β signaling, and suppression of inflammatory cell accumulation and macrophage activation." (PMID 36902112, 2023). "The conclusive evidence from these studies clearly highlighted that certain members of the SP/KLF family (SP1, KLF6, and KLF4) promote the transcriptional regulation of fibrotic remodeling, facilitating the incidence and progression of liver fibrosis." (PMID 36902112, 2023). "An array of sequence-specific transcription factors involved in liver fibrosis, including SMAD, SRF, YAP/TAZ, and Sp1, have been reported to interact with MRTF-A to program the fibrogenic response." (PMID 31681772, 2019). "Their study showed that a ring-type Sp1 decoy ODN suppressed the level of cytokines, TGF-β1 downstream-target genes, and hepatic fibrosis." (PMID 30103395, 2018).
liver fibrosis (continued). "What remains unknown is whether and, if so, how the ability of Sp1 to regulate HSC maturation and liver fibrosis reflects its ability to engage MRTF-A as a co-activator." (PMID 31681772, 2019). "As illustrated in figure seven, B19 NS1 protein aggravates the hepatic fibrosis by enhancing the expression of TGF-β isoforms and activation of Smad2/3, which urge phosphorylated Smad2/3 to cooperate with Smad4 and Sp1 and induce the consequent fiboriss-related proteins, including PAI-1 and α-SMA." (PMID 23840852, 2013).
Parkinson disease (13 papers, 2020 to 2025). A progressive degenerative disorder of the central nervous system characterized by loss of dopamine producing neurons in the substantia nigra and the presence of Lewy bodies in the substantia nigra and locus coeruleus. "ARHGAP26, AXIN1, GJB1, RAB3IP, and SP1 have already been associated with Parkinson’s disease, and PDE4B is known to regulate neuroinflammation." (PMID 35796900, 2022). "Intriguingly, SP1 has been proposed as a key molecule affecting the hub genes implicated in the common mechanisms between T2DM and Parkinson’s disease." (PMID 35420971, 2022). "A previous study revealed that the upregulation of SP1 increased damage to dopaminergic neurons and induced oxidative stress and inflammation in a model of Parkinson’s disease." (PMID 36189232, 2022). "In summary, the results of the present study showed that lncRNA XIST sponges miR-199a-3p to modulate Sp1 expression and further accelerates Parkinson’s disease progression by targeting LRRK2." (PMID 33494069, 2021). "In vitro and in vivo models of Parkinson’s disease were established to investigate the effects of the lncRNA XIST/miR-199a-3p/Sp1/LRRK2 axis." (PMID 33494069, 2021). "It has been found that upregulation of miR-375 attenuates dopaminergic neuronal damage in Parkinson's disease by inhibiting SP1 and attenuating oxidative stress and inflammatory responses." (PMID 34970121, 2021). "In this present study, we also found that the expression of SP1 was increased in Parkinson’s disease progression." (PMID 31927536, 2020). "As for the relationship between SP1 and Parkinson’s disease, some important transcription factors that decide their phenotype were overexpressed in the dopamine neurons, and some of these transcription factors keeping their overexpression into adulthood." (PMID 31927536, 2020). "In this present study, we aim to investigate the roles of miR-375 and the transcription factor SP1 in the protection of dopaminergic neurons in Parkinson’s disease." (PMID 31927536, 2020). "In summary, our study suggests that the up-regulation of miR-375 ameliorated the damage of dopaminergic neurons, reduced oxidative stress and inflammation in Parkinson’s disease by inhibiting SP1." (PMID 31927536, 2020). "In addition, this study suggested that the down-regulation of SP1 ameliorated the damage of dopaminergic neurons, reduced oxidative stress and inflammation in Parkinson’s disease." (PMID 31927536, 2020). "Parkinson’s disease rats treated with overexpressed miR-375 displayed improved neurobehavioral change, ameliorated neuroinflammatory response and oxidative stress, heightened dopamine content and abated neuronal apoptosis by down-regulating SP1." (PMID 31927536, 2020). "Thus, miR-375 and its target gene SP1 have potential as biomarkers and as therapeutic targets for Parkinson’s disease." (PMID 31927536, 2020). "The functions of miR-375 and SP1 in neurobehavioral change, neuroinflammatory response, oxidative stress, dopamine content and expression of apoptosis-related proteins in the substantia nigra of Parkinson’s disease rats were evaluated." (PMID 31927536, 2020). "Up-regulation of SP1 reversed the protective effect of upregulated miR-375 on Parkinson’s disease." (PMID 31927536, 2020). "In addition to that, SP1 inhibition could cooperate with miR-375 to reduce oxidative stress, inflammation, neuronal apoptosis in Parkinson’s disease." (PMID 35091534, 2022). "Altogether, the results in our study demonstrate that overexpression of miR-375 down-regulated the expression of SP1, thus improving the damage of dopaminergic neurons caused by 6-OHDA in Parkinson’s disease, and may play a protective role by reducing oxidative stress damage." (PMID 31927536, 2020). "In previous reports, miR-29c was proved to target specific protein-1 (SP1) and nuclear factor of activated T cells 5 (NFAT5) to inhibit the inflammatory response in Parkinson's disease." (PMID 35433915, 2022).
Parkinson disease (continued). "The results indicated that miR-199a-3p expression was downregulated, whereas that of XIST, Sp1 and LRRK2 were upregulated in Parkinson’s disease." (PMID 33494069, 2021). "The Parkinson’s disease rat models were established by injection of 6-OHDA in two points of the right medial forebrain bundle to explore the role of miR-375 and SP1 in pathological behaviors of 6-OHDA-induced Parkinson’s disease rats." (PMID 31927536, 2020).